PARP1 (poly(ADP-ribose) polymerase 1)
Diseases named in the same sentence as PARP1 in open-access papers (continued):
Sharing a sentence is not in itself a finding about the gene and the disease.
melanoma (continued). "A PARP-1/NF-κB signaling cascade drives the establishment of a pro-tumoral and pro-metastatic SASP in a melanoma xenograft model, though the precise role of NAD+ levels in this context is unknown." (PMID 33371508, 2020). "For example, the binding of PARP1 to NF-κB could activate the expression of melanoma growth stimulatory activity-regulated protein (CXCL1), subsequently improving the progression of melanoma." (PMID 28991194, 2017). "As radioresistance could be associated with high repair capacities that prevent accumulation of DNA damage, we studied PARP-1 expression, activity, and its possible involvement in melanoma radioresistance in a panel of WTBRAF melanoma cell lines harboring different gene alterations." (PMID 37215708, 2023). "Previous studies suggest that PARP-1 overexpression is a potential novel biomarker of aggressive clinical behavior in cutaneous malignant melanoma, but there are no studies focused on the prognostic significance of PARP1 expression in mucosal melanoma patients." (PMID 32380691, 2020). "Furthermore, 20 μM 2HF reduced the IC50 of PARP1 inhibitor in B16-F0 and B16-F10 melanoma cells, but the combination effect on SK-MEL-24 was not statistically significant." (PMID 31615091, 2019). "Therefore, the increase of full-length form of PARP-1 but the lack of PARP-1 cleavage, strongly suggest that these treatments induce DNA damage but do not induce the death for apoptosis of treated melanoma cells." (PMID 31801187, 2019). "Poly (ADP-ribose) polymerase 1 (PARP-1) detects DNA lesions and promotes DNA repair, but can also mediate NF-κB activation upon genotoxic stress, as suppression of NF-κB activity and CCL2 secretion by the PARP-1 inhibitor 3-AB diminishes a secretome in senescent melanoma cells." (PMID 25185441, 2014). "Therefore, we showed that the treatment with (Bu2Sn)2TPPS and with (Bu3Sn)4TPPS, led to a significant increase of the full-length form of PARP-1 that is more evident in A375 and HT-144 melanoma cells treated with (Bu3Sn)4TPPS, but do not induce the cleavage of PARP-1 in treated melanoma cells." (PMID 31801187, 2019). "Therefore, in the light of the data reported, the hypothesis that hydroxytyrosol treatment of melanoma cells induces DNA double strand breaks damage, elicits not only the cleavage of PARP-1 by caspases, but also the increased expression of the phosphorylate form of H2AX." (PMID 33137997, 2020). "The potential interaction between PARP1, IDO1, and PD-L1 has not been studied in a large cohort of mucosal melanomas." (PMID 32380691, 2020).
lung carcinoma (80 papers, 2005 to 2025). "This study demonstrated a novel molecular mechanism underlying the chemopreventive effect of CK in lung cancer cells, involving PARP-1 activation-mediated parthanatos, which is promoted by SIRT6 degradation." (PMID 39940397, 2025). "PARP-1 has been linked to immune modulation in multiple cancers, including breast, ovarian, and lung cancer." (PMID 39201718, 2024). "In this work, we investigate the effect of PARP-1 gene polymorphism on the radiosensitivity of patient with lung cancer, as well as that on the effectiveness of RT." (PMID 36590386, 2022). "In our previous study, it was shown that PARP-1 rs3219073 gene polymorphism was closely associated with the occurrence of lung cancer." (PMID 36590386, 2022). "In line with this, based on associations between this BRCA2 variant and upper aero-digestive tract and lung cancer risk, PARP1 inhibitors were suggested as potential treatment strategies." (PMID 33672545, 2021). "The likely reason is that the frequency of PARP1 mutation in lung cancer was very low and that only one patient with PARP1 mutated lung cancer had concomitant PARP1 mutations in MPLC." (PMID 33707471, 2021). "The PARP1 V762A polymorphism reduces the enzymatic activity of PARP1 and increases the risk of many cancers, such as gastric, cervical, and lung cancers." (PMID 33525741, 2021). "Studies have also shown allelic heterogeneity in PARP1 in specific populations associated with lung cancer." (PMID 33284833, 2020). "Our study shows that CDK4/6 inhibitors, even at sublethal concentrations, cause a considerable decrease in PARP1 transcription, in addition to suppressing lung cancer cell growth." (PMID 29306194, 2018). "In conclusion, this study is the first to show that hydroalcoholic extract of C. aronia L. can decrease the viability of lung cancer cells A549 by causing apoptosis, which was associated with decrease levels of Bcl-2, full length PARP-1 and full-length caspase-3 proteins." (PMID 33112559, 2020). "For example, rs3219073 C>G polymorphism in PARP1 is associated with lung cancer susceptibility, and the carriers of G alleles may have reduced risk of lung AC." (PMID 33284833, 2020). "PARP1 haplotypes may serve as a better predictor in lung cancer development and prognosis compared to single alleles." (PMID 33284833, 2020). "In this study, LSS-11 significantly increased the levels of DR5 and cleaved PARP1, proteins mainly involved in death-receptor-mediated apoptosis, but did not affect mitochondria-associated Bax or Bcl2 proteins in paclitaxel-resistant lung cancer cells." (PMID 29072615, 2017). "Moreover, research has found that loss of PARP1 protein may increase the risk of cancers, such as lung cancer." (PMID 37060095, 2023). "↑PARP1 expression in breast, ovarian, and lung cancers..PARP1 inhibition incervical cancer cell lines:↓Proliferation ↑Cell death↓Metastasis.PARP1 inhibition inliver cancer cells:↓Proliferation ↓Cell migration.PARP inhibition in PC3 and HeLa: ↓Cell migration." (PMID 40722879, 2025). "The combined treatment of Rosa canina extract and cisplatin significantly inhibited lung cancer cell proliferation by downregulating PARP-1 and the TLR2/MyD88/TRAF6/NF-κB signaling pathway, as well as the PI3K/Akt/mTOR pathway." (PMID 40022036, 2025). "We investigated the involvement of silent information regulator 6 (SIRT6) and poly (ADP-ribose) polymerase 1 (PARP-1) in the anticancer effects of CK in lung cancer." (PMID 39940397, 2025). "In lung cancer, PARP1 mediates the AMPK–mechanistic target of rapamycin (mTOR) pathway, which regulates autophagy induced by β‐hydroxybutyrate dehydrogenase 1 (BDH1)." (PMID 40904702, 2025). "This work investigated the involvement of SIRT6 and PARP-1 in the anticancer effects of CK in lung cancer." (PMID 39940397, 2025).
lung carcinoma (continued). "PARP1 has been well known as an oncogene, and its inhibitors are widely used in treating various tumors including lung cancer, especially in SCLC." (PMID 39949782, 2025). "In lung cancer, PARP1 activates the AMPK–mTOR pathway → enhances BDH1‐mediated autophagy → promotes cell proliferation/metastasis; BDH1 overexpression accelerates in vivo tumor growth." (PMID 40904702, 2025). "Parallel to the current results, previous studies reported a high expression of PARP1 in several malignancies including all subtypes of lung cancer especially squamous cell and lung adenocarcinomas enhancing lung cancer survival and metastasis." (PMID 40022036, 2025). "PARP-1 was also shown to transcriptionally regulate vimentin by binding to the promoter of vimentin in lung cancer cells." (PMID 39201718, 2024). "Interestingly, F553L, a K548 neighboring mutation, which is associated with human lung carcinoma based on the Cancer Genome Atlas (TCGA) database revealed, also compromised PARP1 UFMylation, suggesting that deficiency in PARP1 UFMylation may contribute to the development of cancer." (PMID 38657044, 2024). "In this study, we observed that the expression of USP5 promoted the progression of lung cancer cells by the mTOR signaling pathway and interacted with PARP1." (PMID 37060095, 2023). "It has been found that miR-7-5p-mediated downregulation of PARP1 affects DNA homologous recombination repair and the resistance of lung cancer cells to doxorubicin." (PMID 36755223, 2023). "Overall, our findings indicated that ANRIL reduces Rad51 and BRCA1 expression by targeting miR-7-5p/PARP1, which ultimately leads to radiotherapy resistance in lung cancer cells." (PMID 36755223, 2023). "PARP1‐mediated activation of AMPK‐mTOR signalling pathway plays an essential role in BDH1‐induced autophagy in lung cancer cells." (PMID 36919822, 2023). "Inhibition of ADP-ribosylation or knockdown of PARP1 in lung cancer cell lines increased PI3K/AKT signaling, as well as global ATP levels." (PMID 34725336, 2021). "Knockdown and/or inhibition of PARP1 in lung cancer and osteosarcoma cells decreased ERK phosphorylation, which reduced cell proliferation and migration, and increased apoptosis." (PMID 34725336, 2021). "More studies should be conducted to further validate the role of PARP1 in various ethnic groups with different stages and subtypes of lung cancer." (PMID 33284833, 2020). "Next, we decided to conduct a “proof of principle” study to explore the applicability of XRN2 depletion as vulnerability against PARP1 inhibition in lung cancer using A549 cell line model." (PMID 32859985, 2020). "Consistent with concurrent depletion of XRN2 and PARP1 promoting cell death, XRN2-deficient fibroblast and lung cancer cells also demonstrated sensitivity to PARP1 inhibition." (PMID 32859985, 2020). "Biological testing results suggest that these compounds have a strong inhibitory effect on the PARP-1 and possess significant anti-proliferation effects on human lung cancer cells." (PMID 31766720, 2019). "PARP1 transcription was reported to be repressed by lncRNAs in lung cancer, hepatocellular carcinoma, neuroblastoma, thyroid cancer, multiple myeloma, lung morphogenesis and angiogenesis." (PMID 31391118, 2019). "PARP1 upregulates metastasis of lung cancers by improving PARP1-mediated transcription of S1000A4 and CLDN7." (PMID 28991194, 2017). "For instance, Choi’s research demonstrated that inhibition of PARP1 blocked lung carcinoma metastasis in a DNA repair-independent mechanism." (PMID 28991194, 2017). "LSS-11, a novel triazolonaphthalimide-based topoisomerase inhibitor, overcomes paclitaxel-resistance in lung cancer cells via DR5/PARP1-mediated apoptosis and STAT3-mediated downregulation of MDR1 and MRP1." (PMID 29072615, 2017). "We also demonstrated that silencing PARP1 enhanced the cell death induced by the platinum-based chemotherapy drug carboplatin in lung cancer cells (CL1-5 and H1975)." (PMID 27655641, 2016).
lung carcinoma (continued). "We additionally addressed the apoptotic molecular component including PARP1, Bcl2 and Bax in lung cancer cells." (PMID 26754670, 2016). "Further, we showed that silencing PARP1 enhanced the cell death induced by the platinum-based chemotherapy drug, carboplatin, in lung cancer cells." (PMID 27655641, 2016). "In cancer research fields, ectopic miR-1 induced apoptosis through enhanced activation of caspases 3 and 7, cleavage of their substrate PARP-1, and depletion of antiapoptotic Mcl-1 in lung cancer cells." (PMID 21304530, 2011). "Following this line of thought, we found that ANRIL could regulate the miR-7-5p/PARP1 axis in the cytoplasm through website prediction and experimental verification, thereby affecting the radiosensitivity of lung cancer cells." (PMID 36755223, 2023). "In addition, USP5 overexpression upregulated PARP1, while its knockdown downregulated PARP1in lung cancer cells." (PMID 37060095, 2023). "In addition, BDH1, through activating PARP1‐mediated AMPK‐mTOR signalling pathway promoted lung cancer progression." (PMID 36919822, 2023). "Interestingly, the increased expression levels of USP5 protein had significantly promoted the progression of lung cancer cells by the mTOR signaling pathway and interacted with PARP1." (PMID 37060095, 2023). "Combining c-Met and PARP1 inhibitors synergized to suppress the growth of breast cancer cells in vitro and lung cancer xenograft tumor models, which highlighted a treatment with a combination of c-Met and PARP inhibitors in patients bearing tumors with high c-Met expression." (PMID 35847980, 2022). "Interestingly, doxorubicin treatment in lung cancer cells promoted the upregulation of miR-7-5p, which targets PARP1." (PMID 36139424, 2022). "According to our in vitro data, we speculate that BEL is capable of inducing apoptosis in human A549 lung cancer cells by upregulating the levels of caspase-8/3, reducing the level of PARP1, and ultimately, interfering into STAT3/COX-2 pathways." (PMID 33299414, 2020). "The role of PARP1 in lung cancer is yet to be fully understood." (PMID 33284833, 2020). "Poly(ADP-ribose) polymerase-1 (PARP) inhibitors have been FDA-approved for the treatment of breast cancer type 1 susceptibility protein (BRCA1)-mutated metastatic breast cancer, as well as ovarian and lung cancer." (PMID 32373151, 2020). "It has also been suggested that a combination of PARP1 inhibitors with immunotherapies may also be an effective combination treatment for lung cancers, particularly in tumors with other DNA repair defects, such as ERCC1 deficiency." (PMID 32850380, 2020). "Analysis at allelic levels cannot fully explain the function of PARP1 on lung cancer." (PMID 33284833, 2020). "Our study aims to further explore the relation between PARP1 haplotypes and lung cancer." (PMID 33284833, 2020). "Therefore, inhibition of PARP1 expression in combination with other therapeutic regimens should be considered in management and treatment of lung cancer and other forms of cancer." (PMID 30127774, 2018). "Collectively, our data show that LSS-11 is a potent naphthalimide-based chemosensitizer that could enhance cell death in paclitaxel-resistant lung cancer cells through the DR5/PARP1 pathway and STAT3/MDR1/MRP1 STAT3 inhibition." (PMID 29072615, 2017). "The expression of PARP1 in lung cancer with the expression data of TCGA was detected firstly." (PMID 29152079, 2017).
lung carcinoma (continued). "To verify our hypothesis, we treated an LKB1 wild-type lung cancer cell line H358, and three LKB1 deficient lung cancer cell lines, H838, H1355, and H1993, with 6(5H)-phenanthridinone (PHEN), a PARP-1 inhibitor." (PMID 27705915, 2016). "Moreover, we studied the cytotoxic effect of the combination of PARP1 silencing and some chemotherapy drugs for lung cancer, such as carboplatin and pemetrexed, by the MTT assay." (PMID 27655641, 2016). "In addition, miR-224 attenuated TNF-α induced apoptosis by direct targeting of CASP3 resulting in reduction of cleaved PARP1 expression in lung cancer cells." (PMID 26307684, 2015). "In addition, elevated PARP1 expression in lung cancer has also been proposed as a predictive biomarker of PARP inhibitor response." (PMID 25865228, 2015). "Recent emerging evidence indicate the elevated PARP1 expression in lung cancer." (PMID 25865228, 2015). "The data showed that PTL could induce cleavage of apoptotic proteins such as CASP8, CASP9, CASP3 and PARP1 both in concentration- and time-dependent manner in tested lung cancer cells, indicating that apoptosis was trigged after PTL exposure." (PMID 24387758, 2014). "The present meta-analysis provides evidence that the PARP-1 Val762Ala may be involved in cancer development at least in some ethnic groups (Asian) or some specific cancer types (gastric, cervical, and lung cancers, and glioma)." (PMID 24853559, 2014). "Taken together, these findings suggested that BDH1 might be a useful novel biomarker and therapeutic target for lung cancer metastases, and that PARP1‐mediated AMPK‐mTOR signalling pathway played a critical role in BDH1‐induced autophagy, proliferation and metastases." (PMID 36919822, 2023). "However, the knockdown of PARP1 could significantly reduce the proliferation, colony formation, and migration abilities of these selected lung cancer cells." (PMID 37060095, 2023). "Taken together, these findings suggested that BDH1 might be a useful novel biomarker and therapeutic target for lung cancer metastases, and that PARP1‐mediated AMPK‐mTOR signalling pathway might play a critical role in BDH1‐induced autophagy, proliferation and metastases." (PMID 36919822, 2023). "Therefore, we aimed to investigate whether ANRIL could modulate the HR repair pathway through the miR-7-5p/PARP1 axis in lung cancer cells, thereby altering the radiosensitivity of lung cancer cells." (PMID 36755223, 2023). "Hence, we hypothesized that the PARP-1/2 inhibitor rucaparib may improve muscle mass and reduce damage in lung cancer cachectic mice." (PMID 35740560, 2022). "Moreover, in the gastrocnemius muscle of lung cancer-cachectic mice, Parp-1 inhibition through miR-133a, miR-206 and miR-486 seems to promote muscle proliferation and differentiation while Parp-2 inhibition through miR-206 seems to promote muscle differentiation." (PMID 32325796, 2020). "Blocking PARP-1 significantly reduces the levels of ALOX5 and MMP-9 and inhibits neutrophil-mediated lung cancer cell invasion and tumor growth in vivo." (PMID 41155938, 2025). "To explore the role of PARP1/AMPK/mTOR pathway in cell proliferation and metastases in lung cancer, we treated PC‐9 cells with rapamycin and lentivirus transfection." (PMID 36919822, 2023). "Compared with wild-type lung cancer cells, knockdown of ANRIL decreased the expression of PARPA1, while overexpression of ANRIL increased the expression of PARP1." (PMID 36755223, 2023). "The PARP1/AMPK‐mTOR signalling pathway plays an important role in the proliferation and metastases in lung cancer cell." (PMID 36919822, 2023). "Our results also confirmed that PARP1/AMPK‐mTOR‐mediated autophagy played pro‐survival function and promoted the migration and invasion in lung cancer cell." (PMID 36919822, 2023). "It is noteworthy that PARP1 trapping can promote IFN signaling through cGAS-STING components, an outcome similar to that reported for RBN2397 inhibition of PARP7 in lung cancer models." (PMID 37077937, 2023).